CD14 (CD14 molecule)
Description:
Coreceptor for bacterial lipopolysaccharide. In concert with LBP, binds to monomeric lipopolysaccharide and delivers it to the LY96/TLR4 complex, thereby mediating the innate immune response to bacterial lipopolysaccharide (LPS). Acts via MyD88, TIRAP and TRAF6, leading to NF-kappa-B activation, cytokine secretion and the inflammatory response. Acts as a coreceptor for TLR2:TLR6 heterodimer in response to diacylated lipopeptides and for TLR2:TLR1 heterodimer in response to triacylated lipopeptides, these clusters trigger signaling from the cell surface and subsequently are targeted to the Golgi in a lipid-raft dependent pathway. Binds electronegative LDL (LDL(-)) and mediates the cytokine release induced by LDL(-).
Tractability: Small molecule: a drug acting on it is in phase 2 or 3 trials. Antibody: a drug acting on it is in phase 2 or 3 trials; UniProt places it where antibodies can reach, with high confidence; its Gene Ontology location is reachable by antibodies, with high confidence; UniProt predicts a signal peptide or a membrane-spanning region. PROTAC: its protein half-life has been measured; a small molecule that binds it is known.
Target class: Surface antigen
Gene: Protein-coding gene on chromosome 5 (140,631,728 to 140,633,700, reverse strand). Ensembl gene ENSG00000170458.
Subcellular location: Cell membrane; Secreted; Membrane raft; Golgi apparatus
Subcellular location (Human Protein Atlas): Vesicles; Predicted to be secreted
Pathways (Reactome):
Immune System: Activation of IRF3, IRF7 mediated by TBK1, IKKε (IKBKE); ER-Phagosome pathway; IKK complex recruitment mediated by RIP1; IRAK2 mediated activation of TAK1 complex upon TLR7/8 or 9 stimulation; MyD88-independent TLR4 cascade; MyD88:MAL(TIRAP) cascade initiated on plasma membrane; Neutrophil degranulation; Regulation of TBK1, IKKε (IKBKE)-mediated activation of IRF3, IRF7; Regulation of TLR by endogenous ligand; TRAF6-mediated induction of TAK1 complex within TLR4 complex; TRIF-mediated programmed cell death; Toll Like Receptor 4 (TLR4) Cascade; Toll Like Receptor TLR1:TLR2 Cascade; Toll Like Receptor TLR6:TLR2 Cascade; Transfer of LPS from LBP carrier to CD14
Disease: Dengue Virus Attachment and Entry; IRAK4 deficiency (TLR2/4); MyD88 deficiency (TLR2/4); RSV-host interactions; Respiratory syncytial virus (RSV) attachment and entry
Programmed Cell Death: Caspase activation via Death Receptors in the presence of ligand
Gene Ontology:
Molecular function: lipopolysaccharide binding; lipopolysaccharide immune receptor activity; lipoteichoic acid binding; molecular carrier activity; protein binding; opsonin receptor activity; peptidoglycan immune receptor activity
Biological process: cell surface pattern recognition receptor signaling pathway; cellular response to diacyl bacterial lipopeptide; cellular response to lipopolysaccharide; cellular response to lipoteichoic acid; cellular response to molecule of bacterial origin; cellular response to triacyl bacterial lipopeptide; positive regulation of interleukin-8 production; positive regulation of tumor necrosis factor production; toll-like receptor 4 signaling pathway; apoptotic process; cell surface receptor signaling pathway; phagocytosis; positive regulation of cytokine production; positive regulation of toll-like receptor 4 signaling pathway; positive regulation of type II interferon production; lipopolysaccharide-mediated signaling pathway; positive regulation of endocytosis; positive regulation of lipopolysaccharide-mediated signaling pathway; positive regulation of type I interferon production; receptor-mediated endocytosis; response to bacterium; response to molecule of bacterial origin
Cellular component: external side of plasma membrane; extracellular exosome; extracellular region; Golgi apparatus; lipopolysaccharide receptor complex; membrane raft; plasma membrane; endosome membrane; secretory granule membrane; cell surface
Genetic constraint (gnomAD): Loss-of-function variants: 5 observed, 2.98 expected, observed/expected ratio (o/e) 1.68, 90% interval 0.75 to 1.94. That is too few expected variants to judge how well the gene tolerates losing a copy. Missense variants: 478 observed, 534.09 expected, observed/expected ratio (o/e) 0.89, 90% interval 0.83 to 0.96. Synonymous variants: 236 observed, 255.85 expected, observed/expected ratio (o/e) 0.92, 90% interval 0.83 to 1.03.
Homologues: Orthologues: chimpanzee CD14 (98% identical), macaque CD14 (95% identical), rabbit CD14 (73% identical), dog CD14 (71% identical), pig CD14 (71% identical), guinea pig CD14 (70% identical), mouse Cd14 (65% identical), rat Cd14 (63% identical).
Diseases named in the same sentence as CD14 in open-access papers:
CD14 is named in the same sentence as 657 diseases in open-access papers, as found by Europe PMC text mining. Sharing a sentence is not in itself a finding about the gene and the disease. The quoted sentences say what the papers report.
COVID-19 (279 papers, 2020 to 2026). A disease caused by infection with severe acute respiratory syndrome coronavirus 2. "It is worth noting that the A_SC group had a higher proportion of CD14+ monocytes than A_MD group, potentially associated with the exacerbated inflammatory damage in severe/critical COVID-19 cases." (PMID 39148728, 2024). "Of the cell types, SARS-CoV-2 induced CD14 monocyte expansion and NK cell loss, while the B and T cell abundances remained similar between healthy and COVID-19 patients." (PMID 37936693, 2023). "During severe COVID-19, upregulated genes in both CD14 and CD16 monocyte cells were associated with type I interferon signaling, response to the virus, positive regulation of cytokine production, and toll-like receptor (TLR) signaling pathways." (PMID 37936693, 2023). "The CD14+ M5 module was associated with COVID-19 adverse outcome linked pathways as well as fibroblast growth factor stimulation pathways." (PMID 38259488, 2023). "We have defined that the decrease in CD14+/HLA-Dr+ monocyte fraction is associated with mortality in COVID-19 patients." (PMID 35213582, 2022). "Inflammatory HLA-DRhi CD11chi CD14+ monocytes can be considered as a hallmark of mild COVID-19 patients." (PMID 34975340, 2022). "In contrast, anti-inflammatorygenes associated with CD14++ monocytes (M1) weredownregulated in COVID-19 patients relative to that in the HCs." (PMID 32377375, 2020). "The excessive host immune responses mediated by pathogenic T-cells and inflammatory CD14+ CD16+ monocytes that express high levels of IL-6 in blood samples of COVID-19-S patients were also observed in a recent study." (PMID 34676126, 2020). "Based on intracellular cytokine staining, peripheral CD14+CD16+ monocytes are also implicated in the production of inflammatory cytokines in COVID-19." (PMID 32848776, 2020). "Similarly, at the gene level, 205 genes were associated with COVID-19 severity; 125 of these were in all monocytes or CD14+CD16− classical monocytes and 21 were in B cell subsets." (PMID 40532694, 2025). "To evaluate this, first, we leveraged our pre-infection samples and tested whether PLAC8 expression in CD14 monocytes prior to infection was associated with subsequent peak illness severity during COVID-19." (PMID 40532694, 2025). "This suggests that part of the hypermethylated CpG sites in isolated peripheral blood CD14 + might be associated with aberrantly differentiated monocytes released into the bloodstream in severe COVID-19 patients." (PMID 36443794, 2022). "Importantly, the CD14+ monocytes in patients with COVID-19 demonstrate that inflammatory monocytes induce pathogenic T cells, thereby promoting an inflammatory cytokine storm." (PMID 35252273, 2022). "We found association between high ratios of CD14+/CD16+ monocytes and acute infections, as in AA, MA and SA, while those ratios normalized in recovered patients (AP, MP, MR, and SR), but persistently high CD14+/CD16+ monocyte ratios were associated with development of severe COVID-19 in SP." (PMID 35095917, 2021). "Thus, the shift towards more mature CD163+ CD14+ DC3 in COVID-19 patients was associated with inflammation and higher disease activity." (PMID 34614036, 2021). "Similarly, severe COVID-19 cases are associated with increase in Th1 and Th17 cell proportions as well as inflammatory CD14+CD16+ monocytes." (PMID 33623561, 2020). "An increase in the frequency of a CD14−CD16high monocyte population was present in post-COVID-19 conditions, whereas we identified an increase in CD14+CD16+/low monocytes." (PMID 40766325, 2025). "CD14+ monocytes predominantly localized to the subepithelium in acute COVID-19 and surrounded some B cell follicles in convalescent disease, forming a shield around them." (PMID 39890933, 2025). "We found that median expression of CD8, CD14, CD11b, IgG was increased in COVID-19 patients compared to healthy controls across all clusters." (PMID 40244812, 2025).
COVID-19 (continued). "The ISGhi CD163hi CD14+ monocyte subset was exclusively found in four dexamethasone-treated infants with severe COVID-19 (severe T)." (PMID 39877087, 2025). "Flow cytometric analysis confirmed increased expression of CD206, a marker of M2 macrophages, in nasal CD14+ cells in convalescent COVID-19." (PMID 39890933, 2025). "To further explore these effects, we compared the transcriptomes of CD14+ monocytes from severe and severe T COVID-19 cases." (PMID 39877087, 2025). "CD14 was previously reported to be significantly elevated in LongC compared to HC and recovered COVID-19 individuals." (PMID 41369364, 2025). "TLR4 and its downstream signaling molecules, including CD14, MyD88, and TRAF6, are up-regulated in renal tubular and renal endothelial cells in COVID-19 patients, and are closely associated with acute tubular necrosis and increased kidney injury." (PMID 40584714, 2025). "Collectively, the ligand-receptor pair of PF4_CXCR3, in the interaction between CD14+ monocyte and HLA_DR+ Tregs, facilitates the suppression of HLA_DR+ Tregs in severe COVID-19 patients." (PMID 40114921, 2025). "Another pathway enriched in severe/critical COVID-19 in CD14+ monocytes was “neutrophil degranulation”." (PMID 40532694, 2025). "scPanel showed that six genes from CD14+ monocytes were sufficient to provide a high accuracy to identify severe COVID-19 patients." (PMID 39350339, 2024). "In the severe COVID-19 dataset (wilk2020covid), cell-level analysis consistently identified CD14+ monocytes as the most responsive cell type across all subsets, with some variation in the identified genes but a smaller set of stably selected genes." (PMID 39350339, 2024). "The inflammatory storm in COVID-19 is driven by CD14+CD16+ monocytes expressing IL-6, as demonstrated in patients in intensive care units." (PMID 39125849, 2024). "applied single-cell RNA sequencing to 284 samples from 196 COVID-19 patients and reported that the percentage of CD14+ monocytes in PBMCs was significantly elevated in COVID-19 patients, especially in COVID-19 hospitalized and critically ill patients." (PMID 38263182, 2024). "Specifically, intermediate monocytes (CD14+CD16+) of young adults with a severe diagnosis of COVID-19 were more abundant than those found in healthy controls." (PMID 38268832, 2024). "Excessive IL6 is secreted by CD14+ and CD16+ monocytes during COVID-19 progression, which is associated with a systemic inflammatory reaction known as a cytokine storm." (PMID 39555074, 2024). "The proportion of circulating CD14+CD16+ cells in COVID-19 patients was within the normal range, similar to HD (data not shown)." (PMID 39136010, 2024). "Compared to percentages of CASP1+ blood monocytes, BAL-derived monocytes/macrophages (HLADR+CD14+/low CD16−/+) showed increased FLICA CASP1 signal from the patients with COVID-19." (PMID 39240187, 2024). "Patients with COVID-19 have been found to harbor a unique subset of monocytes with a distinct immunophenotype, namely expression of CD14 and CD16, and FSC-high." (PMID 38921181, 2024). "Severe/critical Delta COVID-19 is accompanied by depletion of classical CD14 monocytes and enrichment of Mon IFI30." (PMID 39712003, 2024). "The size of CD16+ and CD14+ monocyte clusters were smaller in COVID-19 than in HC samples, consistent with iron scavenging and trafficking to tissues." (PMID 38429458, 2024). "Patients with severe COVID-19 exhibit less pronounced increases in TLR4 expression on CD14 monocytes than those with mild COVID-19, which is related to activation of TLR4/NF-κB axis after lipopolysaccharide stimulation." (PMID 38455049, 2024). "In these clusters, the proportion of cells from severe COVID-19 patients reached over 75%, marginally higher than the overall proportion of ‘severe cells’ in the CD14 monocytes population (53%), suggesting a potential ‘severe’ signature." (PMID 39705183, 2024).
COVID-19 (continued). "First, we identified that the higher expression of CD3 is a characteristic of the severe forms of sepsis and COVID-19; this same pattern was observed for the gene CD14." (PMID 38892107, 2024). "We analyzed the percent-positivity of these and other markers on CD14+, CD16+, and CD83+CD14+ monocytes, and observed upregulation of these markers among COVID-19 patients compared to healthy donors across multiple monocytes states." (PMID 39041028, 2024). "CD71 expression was also elevated on CD16+ and CD14+ monocytes of patients with COVID-19 compared with HCs." (PMID 38429458, 2024). "Elevated expression of TGFB1 in CD4+ T cells and higher numbers of TGFB1-expressing T and CD14-positive cells have been observed in a small set of patients with severe COVID-19." (PMID 37255317, 2023). "Significantly increased levels of membrane antigens were found in the severe COVID-19 patients’ EVs that originated from monocyte or macrophages cells (CD14-expressing EVs, p = 0.012) compared to the EVs of the mild COVID-19 patients (p = 0.0186)." (PMID 36982991, 2023). "Another study reported that patients with COVID-19-induced ARDS had a higher proportion of CD14+ monocytes, accounting for approximately 50% of the total number of cells." (PMID 37363730, 2023). "In this study, we first found that eight inflammasome-related genes were downregulated in CD14+ monocytes from COVID-19 patients." (PMID 38004809, 2023). "In agreement with this notion, a significantly higher frequency of CD14+CD16+ monocytes was found in the peripheral blood of COVID-19 patients compared to healthy donors." (PMID 37818368, 2023). "We also identified the substantial expression of SELL (an ISG) in most CD14 monocyte cells in severe COVID-19." (PMID 37936693, 2023). "Elevated MCEMP1 and reduced HLA-DRA gene expression in CD14+ cells during the early phase of disease are prognostic of severe COVID-19." (PMID 36801619, 2023). "We demonstrate TOSICA’s advantages by applying it to scRNA-seq data of tumor-infiltrating immune cells, and CD14+ monocytes in COVID-19 to reveal rare cell types, heterogeneity and dynamic trajectories associated with disease progression and severity." (PMID 36641532, 2023). "Understanding the role of CD14+CD16+ monocytes in COVID-19 pathogenesis is crucial for developing effective therapies to manage the cytokine storm and prevent severe disease outcomes." (PMID 37818368, 2023). "Single cell RNA sequencing revealed that the upregulation of MCEMP1 and downregulation of HLA-DRA transcripts in severe COVID-19 subjects were seen in CD14+ immune cell subsets, which are primarily myeloid lineage cells." (PMID 36801619, 2023). "Pathogen recognition receptor (PRR) RIG-I/MDA5 and GPCR pathways displayed differential behaviour in CD8+ T cells and CD14+ monocytes in severe COVID-19 (D1) and during remission (D5 and D7)." (PMID 36732632, 2023). "With respect to monocytes and COVID-19 outcome, Zhou and colleagues investigated the pathological role of CD14+CD16+ monocytes in patients with severe pulmonary syndrome." (PMID 37818368, 2023). "Compared with healthy donors and convalescent patients, the inflammasome pathway score was downregulated among the CD14+ mononuclear cells, mononuclear dendritic cells, and dendritic cells of the COVID-19 patients." (PMID 38004809, 2023). "Among these genes are CD14, CSF2, and CXCL10, which are linked to COVID-19 related cytokine storm (CD14 and CXCL10) and acute respiratory syndrome (ARDS) (CSF2/GM-CSF)." (PMID 36980301, 2023). "We observed a decrease in the number of DCs and CD16+ monocytes, as well as a significant increase in the proportion of CD14+ monocytes in COVID-19 patients." (PMID 36817436, 2023). "The integrated cell-cell communication network analysis revealed that CD14 monocytes and NK cells exhibited the highest degree of communication weight, while platelets enhanced communication with other cell types in COVID-19." (PMID 38022594, 2023).